CD4 (CD4 molecule)
Diseases named in the same sentence as CD4 in open-access papers (continued):
Sharing a sentence is not in itself a finding about the gene and the disease.
eosinophilia (116 papers, 2005 to 2025). "Of relevance in chronic disease, peripheral eosinophilia was associated with decreased CD4+ T cell infiltration in the upper perifollicular area." (PMID 39282571, 2024). "T-bet deficiency thus underlies the excessive production of Th2 cytokines, particularly IL-5 and IL-13, by CD4+ αβ T cells, causing blood eosinophilia and UAI." (PMID 35909394, 2022). "The second pattern was a Th2-biased CD4 T cell response associated with eosinophilia and neutrophilic alveolitis." (PMID 29073183, 2017). "Tbet deficient mice exhibited pronounced airways eosinophilia and mucus production in response to RV infection that, by utilising a CD4+ cell depleting antibody, were found to be T helper cell dependent." (PMID 27683080, 2016). "Presence of eosinophilia has been reported as associated with low CD4+ T-cell count or low nadir CD4+ T-cell count in HIV infection in other studies." (PMID 24010677, 2013). "Sézary's syndrome (a peripheral T-cell neoplasm) has been associated with elevated IgE and/or eosinophilia when the malignant clone is of the CD4+ helper phenotype and produces an abnormal amount of the cytokine IL-4." (PMID 20016775, 2009). "A Th2-skewing of T-bet-deficient CD4+ cells may also cause inflammation of the upper respiratory tract, peripheral eosinophilia, and an increase in Th2-cytokines IL-4, IL-5, and IL-13." (PMID 38835658, 2024). "Age between 40 and 50 years (OR 2.50, 95% CI 1.13–5.50), refugee status (3.55, 1.72–7.33), country of origin within Africa (6.15, 2.44–18.60), eosinophilia (3.56, 1.25–10.16) and CD4 count < 200 cells/mm3 (2.46, 1.02–5.92) were associated with positive Schistosoma serology." (PMID 31992216, 2020). "These authors were able to show, in CD4-deficient mice, that the first increase, at 10 days p.i., was part of the innate immune response, whereas the second peak in eosinophilia, at 3 weeks p.i., was dependent on CD4 T cells and was a part of the adaptive immune response." (PMID 26135397, 2015). "Together, these data show that depletion of CD11c+ cells (including pDCs, cDC1s, CD301b+cDC2s and AlvMΦs) reduces eosinophilia, and both type 2 and type 17 cytokine production by CD4+ T cells, in the pulmonary response to Af spores." (PMID 39843887, 2025). "Coinciding with these pathological alterations, SOX9 loss dramatically altered hepatic immune cell responses, including more pronounced eosinophilia, a reduction in CD4+ T cell proportions and heightened frequency of Ly6lo monocytes." (PMID 40489560, 2025). "These cytokines, produced by a subpopulation of CD4 T cells, stimulate type 2 immunity, which is characterized by high levels of IgE antibodies and eosinophilia." (PMID 40125009, 2025). "By d12, anti-CD4 mAb treated mice showed a dramatic reduction of eosinophilia and neutrophilia in the BAL fluid and lung tissue." (PMID 39843887, 2025). "ILC2s and a subpopulation of CD4+ T cells known as Th2 cells can secrete IL-4, IL-5, and IL-13 and stimulate type 2 immunity with high IgE antibodies and eosinophilia." (PMID 37152304, 2023). "CD4+ T cells show Th2 skewing and production of IL-4, IL-5, IL-13, contributing to the atopic phenotype seen in these patients of eczema and eosinophilia." (PMID 37727514, 2023). "For example, in patients with Strongyloides and HIV coinfection, the researchers found a significant inverse correlation between the survival rate, the CD4+ T-cell counts, and peripheral eosinophilia." (PMID 37235296, 2023). "This also reduced their expression of Gata3, Il4, Il5, and Il13 in lung conventional CD4+ T cells: these effects markedly reduced the eosinophilia and AHR." (PMID 37917548, 2023). "The eosinophilia observed has been described previously and is likely due to the release of IL-5 and GM-CSF release by IL-2-stimulated CD4-positive lymphocytes." (PMID 36765608, 2023). "Laboratory investigations showed elevated IgE, eosinophilia, low percentages of CD4+ T cells, and low IgM levels." (PMID 36703986, 2022).
eosinophilia (continued). "Our results showed that T cells CD4 memory resting and eosinophilia activated were significantly positively correlated with PRDM5expression." (PMID 35799142, 2022). "The MSMD of this patient results from defective IFN-γ production by innate and innate-like adaptive lymphocytes, whereas the UAI and eosinophilia result from excessive Th2 cytokine production by adaptive CD4+ αβ T lymphocytes." (PMID 35909394, 2022). "The granuloma cell population is in general a large aggregation of mononuclear phagocytes, plasma cells, neutrophiles, fibroblasts, and lymphocytes, but is typically composed of 50% eosinophilia, 30% macrophage, and 20% CD4+ T cells." (PMID 34281269, 2021). "CD4+FoxP3+ Tregs can reduce eosinophilia, impair humoral responses and secret an inhibitory cytokines, such as IL-10 and TGFβ, which suppress the effector functions of activated T cells and reduce inflammation." (PMID 33101290, 2020). "A lower eosinophilia was detected in LPS-pretreated mice, along with an increase in phagocytes and regulatory cells (CD4+CD25+FOXP3+ and CD4+IL-10+), together with higher levels of IL-12 and TNFα." (PMID 32379832, 2020). "It was earlier reported that atypical eosinophilia in RSV infected BALB/c mice was triggered by vaccination with G peptide (aa 184–198) in a CD4—dependent mechanism." (PMID 30142227, 2018). "The effector cell types and mechanisms at play in both allergic and helminth infection settings appear to be very similar, being dominated by eosinophilia, CD4+ Th2 cells, alternatively activated macrophages and GATA3+ type 2 innate lymphoid cells (ILC2s)." (PMID 27256370, 2016). "Laboratory findings include decreased peripheral CD3 and CD4, defective burst test, as well as few cases of eosinophilia." (PMID 27222657, 2016). "Depletion of CD4+ T cells resulted in a near complete reversal of RV induced eosinophilia and mucus production, suggesting that these features were indeed dependent on CD4+ T cells." (PMID 27683080, 2016). "Foxp3 acts as a master switch gene for CD4+CD25+Treg cell development and function, and a mutation in Foxp3 leads to hyper-IgE, eosinophilia and dysregulated Th1 and Th2 cytokine production." (PMID 26445348, 2015). "In summary, we report for the first time that in utero and postnatal vitamin D deficiency, with concomitant inhaled allergen exposure in the neonatal period, results in increased airway eosinophilia and Th2 cells and reduced CD4+IL-10+ T regulatory cells." (PMID 24943330, 2014). "In order to maintain the immunogenicity while eliminate CD4+ T cell epitope-mediated eosinophilia, mGcf which lost the function of CD4+ T cell epitope and Th-mGcf was generated." (PMID 24736750, 2014). "We have recently shown that BLT2 negatively regulates airway eosinophilia via suppressing the activation of IL-13-producing CD4+ T cell in OVA-sensitized/challenged mice." (PMID 23452625, 2013). "Sensitized mice were protected from airway eosinophilia when treated with anti-CD4 in the presence of the same antigen used for sensitization (OVA >tOVA and β-LG >tβ-LG)." (PMID 21818308, 2011). "High Ascaris IgE subgroups (egg+IgEhi and egg-IgEhi) had eosinophilia, highest viral loads, and lower CD4+ counts in the HIV- group)." (PMID 21999928, 2011). "The egg+IgEhi subgroup displayed lymphocytopenia, eosinophilia, (low CD4+ counts in HIV- group), high viral load (in HIV+ group), and an activated lymphocyte profile." (PMID 21999928, 2011). "In particular, SOX9 deficiency led to the dispersed arrangement of F4/80+ cells and altered CD4+ T cell phenotypes, with pronounced eosinophilia and monocyte recruitment; potentially suggesting signals from the fibrotic ECM help tether immune cells to the granuloma or modulate their function." (PMID 40489560, 2025).
eosinophilia (continued). "In vivo, CD4-specific conditional IP KO mice (CD4Cre+IPflox) exhibited exacerbated lung inflammation following exposure to Alternaria alternata extract, marked by increased IL-5 and IL-13 production, enhanced eosinophilia, and elevated mucus production." (PMID 40587812, 2025). "In addition, Th2-type inflammation, CD4+ recruitment, eosinophilia, and goblet cell mucus production decreased in this murine genetic background compared to wild-type animals." (PMID 36675006, 2023). "Airway eosinophilia in CC011 mice was completely dependent upon CD4+ T-cells." (PMID 37296458, 2023). "Therefore, eosinophilia, along with low CD4, CD8 T cells, and activated inflammatory response, are likely to be significant prognostic factors for the disease severity." (PMID 37217986, 2023). "A population of non-Th2 IL-21–secreting CD4 T cells has also been observed in the lungs after allergen challenge, which provides essential cues to IL-21R–expressing lung-resident Th2 cells and enhances eosinophilia." (PMID 37163370, 2023). "Given the major role of IL-5 in the recruitment of eosinophils, this likely explained why FTY720 treatment was ineffective in substantially reducing eosinophilia even though the accumulation of the majority of memory phenotype CD4 T cells was impaired upon HDM exposure." (PMID 35936001, 2022). "However, mice receiving CD4+ T cells from donors undergoing neutrophil depletion during sensitization displayed very robust eosinophilia." (PMID 35191395, 2022). "The mechanism for the development of small airway lesions in children with atopy may be eosinophilia and an abundance of CD4+ T lymphocytes in the small airways compared to that in the larger airways, which results in small airway inflammation." (PMID 34627176, 2021). "We found that Major Histocompatibility Complex Class II (MHCII) deficiency and lack of conventional CD4+ T cells had the most profound effect, essentially ablating airway eosinophilia and goblet cell hyperplasia in all models." (PMID 31164097, 2019). "Eosinophilia, inverted CD4/CD8 ratio, and increased IgE level were described." (PMID 27222657, 2016). "Moreover, pICLC treated mice displayed diminished GATA3+ IL-5 producing CD4 T cells and dramatically reduced eosinophilia, but increased RORγt+ IL-17A producing CD4 T cells." (PMID 26252005, 2015). "In particular, alum adjuvant in FI-RSV vaccine formulations has considerable impacts on increasing immunogenicity and virus clearance as well as Th2 type CD4 T cells, proinflammatory cytokines, eosinophilia, mucus production, B220+ pDCs, and CD4+ DCs, and inhibition of effector CD8 T cells." (PMID 26468884, 2015). "Immunological assays showed eosinophilia and an increase of CD4 cells but not an increase of the tumor causing cytokine IL-6 negating doubts of safety." (PMID 28324460, 2014). "Whereas IL-13-producing CD4+ T cells and ILCs are located in the tissue and regulate worm expulsion and eosinophilia, IL-4 producing CD4+ T-follicular helper cells (TFH) are concentrated in draining lymph node and drive the humoral response following N. brasiliensis infection." (PMID 22795966, 2012). "Furthermore, both subgroups with elevated IgE (egg+IgEhi and egg-IgEhi had eosinophilia, low CD4+ counts (especially in the HIV- group) and three-fold higher viral load (in HIV+group) compared to the low IgE subgroups (the egg+IgElo and egg-IgElo)." (PMID 21999928, 2011). "Likewise, among the HIV uninfected individuals, both groups with high IgE (egg+IgEhi and egg-IgEhi) had marked eosinophilia and lower CD4+ counts." (PMID 21999928, 2011). "Although ILC2 are numerically fewer than CD4+ Th2 cells in asthmatic lungs (10,000-fold fewer), the cell produces up to 100-fold more T2 cytokines than the latter on a cell-per-cell basis and likely contributes to the persistence of eosinophilia in the airways." (PMID 37947634, 2023).
eosinophilia (continued). "Additionally, ILC2 may be the main driver of eosinophilia and asthma symptoms in conditions where CD4+ T cell activity has been dampened by steroid therapy recapitulated as knocking out recombinase activating gene (Rag−/−) in mice models." (PMID 37947634, 2023). "Interestingly, we found a significant increase in IFNγ production in both CD8+ and CD4+ T cells in the lungs of IL5Tg mice compared to both WT and Δdbl-IL5Tg mice, suggesting that eosinophilia and reduced tumor burden in IL5Tg mice correlates with increased proportions of IFNγ producing T cells." (PMID 35756626, 2022). "In addition, the percentage of Th2 cells in the CD4+ T cells was almost equivalent in both groups; however, significant functional dissimilarities including a prominent level of IgE, Th2 pattern of cytokine levels, and eosinophilia were noted in the patients." (PMID 28740493, 2017). "Evaluation of only one or two disease parameters such as eosinophilia, histopathology or AHR, may overlook disease exacerbation in terms of weight loss or airway obstruction that is mediated by a distinct subset of memory CD4 T cells." (PMID 25769044, 2015). "Accordingly, we have also shown in this study that CD4+ T cell epitope within RSV A2 Gcf is directly correlated, not only with the induction of RSVG-specific antibody responses and viral clearance, but also with the vaccine-mediated eosinophilia and severe body weight loss." (PMID 24736750, 2014). "Moreover, recent analysis of Tbet−/− mice has revealed that dysfunction of Tbet may be involved in the pathogenesis of allergic airway disease and that Tbet+CD4+ cells can inhibit Th2-mediated eosinophilia." (PMID 23291461, 2013). "OVA-mRNA-LNP–treated mice displayed reduced airway resistance, decreased eosinophilia, diminished proportion of Th2 (GATA3+) cells, and increased IFN-γ+ CD4+ T cell frequency, paralleling the acute response." (PMID 40985871, 2025). "Bone marrow flow cytometry demonstrated eosinophilia and 3% atypical T-cells with an immunophenotype of CD3−, CD4+, CD2+, CD5+, CD7−, CD8−." (PMID 41488087, 2025). "Similar to the spleen, blood CD4 and CD8 T-cell counts, neutrophilia and eosinophilia were detected in the imiquimod-treated CD1a-Tg mice." (PMID 36477177, 2022). "Helminths-driven immune modulation in these conditions included reduced CD3+, CD4+, CD8+, natural killer (NK), CD4+CD25high and IFN-γ responses, but increased eosinophilia, Tregs, IL-4, IL-5 and IL-10 responses." (PMID 34220854, 2021). "We compared four models, which use the allergens OVA or HDM and employ different protocols of allergen sensitisation and challenge, focusing on airway eosinophilia and goblet cell hyperplasia as these responses can be elicited by either ILC2 or CD4+ Th2 cells." (PMID 31164097, 2019). "Targeted CD4+CD25+ Tregs significantly reduced AHR, airway eosinophilia, mucus hyper-secretion, Th2 cytokine production, and allergen-specific IgE after sensitization with a model allergen." (PMID 28955341, 2017). "Immunological hallmarks of allergic asthma include eosinophilia in patient bronchoalveolar lavage (BAL) fluid, sputum or bronchial biopsies, Th2 polarised CD4+ T cells secreting type 2 cytokines (including IL-4, IL-5 and IL-13), and IgE antibody." (PMID 27256370, 2016). "Strikingly, T. muris-infected mice depleted of CD4+ cells were protected from papain-induced AAI, based on a persistent reduction of airway eosinophilia compared to uninfected control mice." (PMID 26644379, 2016). "CD4+ T cells from Schistosoma mansoni-infected SOCS2-/- mice expressed high Type-2 responses after challenge: high levels of IgE, Type-2 responses, eosinophilia and inflammatory pathology compared to wild-type individuals." (PMID 25867089, 2015).
eosinophilia (continued). "Indeed, we found that pICLC treatment greatly suppressed the development of eosinophilia normally observed in C. neoformans infection, indicating that the effect on eosinophil numbers in the lungs may be due to the impact of pICLC on CD4 T cell effector polarization in C. neoformans infected mice." (PMID 26252005, 2015). "DIDS laboratory findings can reveal, in addition to elevated IgE and eosinophilia seen in AD-HIES, low absolute lymphocyte counts, low total T-cell counts, with low CD4+ and low CD8+ counts but normal CD4+ to CD8+ ratio." (PMID 23283142, 2012). "As previously observed in the C57BL/6 system, CD4+ and CD4− MLNC showed equivalent efficacy at reducing total airway cell infiltration and eosinophilia in recipient mice." (PMID 20306466, 2010). "Passive introduction of CD4+ T cells isolated from RSV-infected mice into naïve mice followed by intranasal administration of RSV led to severe lung damage and eosinophilia." (PMID 17270047, 2007). "Mice given CD4+ T cells from donors that received either no antibody or IC antibody during sensitization displayed only modest eosinophilia after 3 challenges." (PMID 35191395, 2022). "Accordingly, many eosinophils were found in one skin biopsy in which IL-5 expression was detected along with the presence of CD4+ and a low number of CD8+ T cells, and five of the eight subjects showing increased serum IL-5 levels at the time of ADRs had eosinophilia." (PMID 35938810, 2022). "The results of immune cell infiltration show that there are more CD4 or CD8 T cells, helper T cells, M1 macrophages, activated dendritic cells, and eosinophilia infiltrated in the TCMR group (Supplementary 3A, B), which are precisely the immune cell types significantly related to m6A regulators." (PMID 36483557, 2022). "In addition to increased eosinophilia, the expressions of HLA-DR, CD38, CD28, CCR5, Ki67 in CD4+ as well as CD8+ T cell subsets among Africans is significantly higher when compared to Europeans." (PMID 34220854, 2021). "In comparison, anti-IL-17 antibody treatment effectively reduced neutrophilic infiltration and increased CD4+FoxP3+ cells, but it induced lung eosinophilia and did not decrease histopathology scores." (PMID 30104645, 2018). "Consistent with the higher percentage of CCR4+CD45RA−CD45RO+CCR7+ CD4+ T cells in patients without blood eosinophilia, atopic asthma patients without blood eosinophilia showed an increase of CRTH2+CD45RA−CD45RO+CCR7+ CD4+ T cells, compared to control subjects." (PMID 29507584, 2018). "Patients without blood eosinophilia showed a significantly higher percentage of CCR4+ CD4+ T cells (left)." (PMID 29507584, 2018). "Both Th1 CD4+T cells and type 1 (Tc1) CD8+T cells may contribute to the suppression of Th2 responses, eosinophilia, as well as IgE production." (PMID 29302700, 2018). "Alum in FI-RSV was found to be responsible for inducing eosinophilia, mucus production, and lung histopathology by increasing RSV specific IL-4+ an TNF-α+ Th2 CD4+ T cell responses, and the mobilization of multiple DC subsets including CD11b+, CD103+, pDCs, and CD4+ DCs." (PMID 26468884, 2015). "Sensitization with OVA-alum or HDM-alum did not lead to airways eosinophilia in mice previously exposed to the same antigens under the cover of non-depleting anti-CD4." (PMID 21818308, 2011). "Treatment with IP results in eosinophilia and an increase of CD4 cells but not in an increase of IL-6 or CRP." (PMID 22114899, 2011). "Adoptive transfer of CD8+, but not CD4+ T lymphocytes from naïve CD3IL-5+ or C57BL/6 wild type mice restored BM eosinophilia in immunodeficient SCID-bg mice." (PMID 16740158, 2006). "Transfer of CD3IL-5+ CD3+ T cells induced blood eosinophilia in SCID-bg mice compared to the 0.9% NaCl-injected control animals and the animals that had been given CD3IL-5+ CD4+ T cells (27 ± 8 vs. 0.6 ± 0.2 and 5 ± 3 × 104/ml; P = 0.001 and 0.015, respectively)." (PMID 16740158, 2006).